ABCB5 (ATP binding cassette subfamily B member 5)
Diseases named in the same sentence as ABCB5 in open-access papers (continued):
Sharing a sentence is not in itself a finding about the gene and the disease.
melanoma (continued). "ABC transporters family, and mainly ABCB5, have been shown to induce the tumour progression and multidrug resistance of melanoma cells through regulation of the drug’s efflux in melanoma cells, especially when they are co-expressed with CD133." (PMID 35334544, 2022). "Peripheral blood, primary tumor or metastases at an advanced stage (IV) that present RANK+-melanoma cells, co-express ABCB5, MART-1 and CD133." (PMID 35565234, 2022). "In the study, the ABCB5+ subpopulation exhibited self-renewing and differentiating phenotypes in addition to playing significant roles in melanoma growth, tumourigenicity and metastasis." (PMID 35740696, 2022). "We enriched and analyzed CMCs from melanoma patients (AJCC staged ≥ pT1b) using CD146 and ABCB5 as melanoma-specific epitopes." (PMID 34830300, 2021). "Despite CMCs being phenotypically and molecularly heterogeneous, we decided to use CD146 as a capture antigen, as it is expressed up to 80% in MM, together with the melanoma-initiating marker ABCB5." (PMID 34830300, 2021). "Another functional driver of melanoma aggressiveness and drug resistance is ATP-binding cassette sub-family member 5 (ABCB5), which promotes drug efflux in cancer cells." (PMID 35048028, 2021). "In the case of ABCB5+ melanoma initiating cells, the expression of HLA molecules was shown to be lower as compared with the ABCB5− melanoma non-stem cells." (PMID 33918136, 2021). "Melanoma tumors contain cancer stem cells, with a long-lasting renewable capacity and expression of a multidrug resistance pump called ATP-binding cassette sub-family B member 5 (ABCB5)." (PMID 33738260, 2021). "It has been shown that ABCB5 can keep melanoma-initiating cells by a pro-inflammatory cytokine signaling pathway." (PMID 34051847, 2021). "So, these findings documented in a more enlarged case series allowed us to develop a highly effective homemade CMC enrichment protocol, selecting CD146 and ABCB5 as melanoma-specific epitopes, even in “clinically remission” patients." (PMID 34830300, 2021). "More recently, P-gp (Abcb1) has been also identified in human and pig RPE, and Abcb5 protein, which is highly homologous to Abcb1, was found in melanoma cells and intact melanocytes." (PMID 33804686, 2021). "Current studies have shown that the metastasis of melanoma is related to the expression of certain genes and the activation of certain pathways, such as ABCB5 expression, lncRNA KCNQ1OT1, the MMP-9 signaling pathway, and the HGF-MET signaling pathway." (PMID 34582363, 2021). "Frank and coworkers demonstrated that ABCB5 was overexpressed and caused resistance to doxorubicin in CD133+ circulating melanoma cells." (PMID 32823711, 2020). "ABCB5-positive cells were significantly enriched in spheres compared with adherent cells in OCR_OCMM1 and OCR_OCMM2 canine melanoma cells (3.5- and 9.5-fold enrichment, respectively)." (PMID 32423311, 2020). "Gene expression analysis of five melanoma-associated genes, including MLANA, TYR, MAGEA3, ABCB5 and PAX3, showed that at least one transcript was detected in 18 out of 43 samples analysed (42%)." (PMID 32037400, 2020). "There are several proteins associated with the malignancy of melanoma in particular, such as S100, CD133, and ABCB5." (PMID 33114317, 2020). "One non-canonical peptide, KYKDRTNILF, derived from the downstream ORF (dORF) of the melanoma stem-cell marker ABCB5 gene in 0D5P, was also found to be immunogenic in both autologous CD8+ TILs and CD8+ T cells from peripheral blood lymphocytes (PBLs)." (PMID 32157095, 2020). "Analysis of RNA suggested that CSPG4+ CTCs were distinct from CTCs enriched by another melanoma marker, ABCB5." (PMID 32984308, 2020). "Giant cells were positive with melanoma maker S100 and cancer stem cell markers including ABCB5 and CD133 in vitro and in vivo." (PMID 33114317, 2020).
melanoma (continued). "Whilst the same CSC markers can be found in different cancers, some cancers have distinct markers for example melanoma CSCs are ABCB5+ whilst medulloblastoma CSCs are CD15+." (PMID 32823711, 2020). "Sztiller-Sikorska showed that bryostatin-1 is able to kill ABCB5 (ATP-binding cassette, sub-family B, member 5)-positive melanoma stem-like cells." (PMID 32283669, 2020). "CMCs are phenotypically and molecularly heterogeneous, thus we performed a “home-made Liquid-Biopsy,” by targeting the melanoma-associated-antigen, MCAM/MUC18/CD146, and/or the melanoma-initiating marker, ABCB5." (PMID 32548126, 2020). "Previously, it has been shown that inhibition of the Akt pathway increased the pool of melanoma stem cells through enhancing ABCB5 functionality." (PMID 32357409, 2020). "In human SK-MEL-30 melanoma cells treated with 250 ng/mL hGH in vitro increased expression of ABCB5, ABCB8, ABCG1 and ABCG2 RNA." (PMID 33291663, 2020). "An immunofluorescent analysis of the melanoma tissues unveiled a stronger immunostaining of ABCB5 and CD133 in the giant cells of the cisplatin-treated tumors." (PMID 33114317, 2020). "Quantitative analysis confirmed an increase in the number of external melanoma cells with high ABCB5 immunofluorescence intensity upon drug treatment, while internal melanoma cells were apparently unaffected in that respect." (PMID 31035967, 2019). "The significant enrichment of EMT genes in ABCB5-enriched CTCs is interesting since EMT is a process in melanoma by which the melanoma cells lose their melanocytic phenotype and acquire a more invasive phenotype." (PMID 30769764, 2019). "Remaining intact external melanoma cells showed a significantly increased amount of ABCB5-immunoreactivity." (PMID 31035967, 2019). "Although ABCB5 is present in several human tissues, it is highly abundant in melanocyte progenitors, melanoma cell lines, and melanoma biopsies." (PMID 31035967, 2019). "(A and D) Overlay images of the confocal sections shown in B and E. In overlays, ABCB5 signals, melanoma cells, keratinocytes, and nuclei are depicted in red, green, yellow, and blue, respectively." (PMID 31035967, 2019). "In general, our results fit nicely to previous studies, which reported that ABCB5 expression is enhanced in malignant melanoma, that it has a functional role in tumor growth, and that chemotherapy leads to the selection of ABCB5-expressing cells." (PMID 31035967, 2019). "ABCB5, an ATP-binding cassette, is a melanoma ‘stem cell’ marker of a slow-cycling population of tumour cells with self-renewal, proliferation, differentiation, and tumorigenicity capabilities." (PMID 30769764, 2019). "A third difference between external and internal melanoma cells was related to their expression of the ATP-dependent transporter protein, ABCB5." (PMID 31035967, 2019). "Previously, ABCB5 expression has been associated with melanoma progression and resistance, yet it is unclear how ABCB5 drives melanoma spreading." (PMID 30769764, 2019). "The finding of PI3K/AKT in ABCB5 CTCs is interesting as the PI3K-AKT signalling pathway has been shown to regulate the quiescence of melanoma stem-cells characterised by high ABCB5 expression." (PMID 30769764, 2019). "In fact, treatment of melanoma with multiple anticancer compounds such as dacarbazine and vemurafenib also leads to selection towards ABCB5-enriched tumors." (PMID 31547367, 2019). "On the other hand, ABCG2 is responsible for the resistance of hepatocellular CSCs to 5-fluorouracile, mephedrone, and cisplatin, whereas ABCB5 was found on circulating melanoma cells resistant to doxorubicin." (PMID 30834247, 2019). "The few remaining external melanoma cells, however, showed a significantly increased amount of ABCB5-immunoreactivity." (PMID 31035967, 2019). "We profiled the gene expression of CTC subpopulations immunomagnetic-captured by targeting either the melanoma-associated marker, MCSP, or the melanoma-initiating marker, ABCB5." (PMID 30769764, 2019).
melanoma (continued). "Cancer stem cell properties of MACS-sorted CD133(+) BAK-P melanoma were previously verified by immunofluorescent staining and qRT-PCR analysis for stem cell markers, including Oct 3/4, Nestin, and ABCB5." (PMID 31623313, 2019). "ABCB5 was differentially expressed in response to different chemotherapeutic drugs in different melanoma cells." (PMID 29929490, 2018). "The differential expression of ABCB5 protein was consistent with the differential expression of ABCB5 mRNA in the three PLX-resistant melanoma cell lines." (PMID 29929490, 2018). "This research group also reported that melanoma patients had enriched ABCB5-expressing cells in vivo after clinical TMZ therapy." (PMID 29929490, 2018). "Our study provides different insights into the function of ABCB5 in melanoma chemoresistance to BRAF inhibitor." (PMID 29929490, 2018). "Our previous research has also shown that ABCB5 was highly expressed in the sentinel lymph nodes of melanoma patients who experienced recurrence." (PMID 29929490, 2018). "Our work provides further insight into the role of ABCB5 in BRAF inhibitor-resistant melanoma cells." (PMID 29929490, 2018). "We found that both A375 and BLM melanoma cells express the surface stem cell markers ABCB5 and CD44, as evaluated by Western blotting and by immunofluorescence analysis; on the other hand the stem cell marker CD271 is expressed only in A375 cells." (PMID 29330434, 2018). "Inhibition of ABCB5 can increase intracellular drug accumulation and confer melanoma cells’ sensitivity to doxorubicin." (PMID 29929490, 2018). "In experimental models, ABCB5 knockdown reduced the migratory capacity of melanoma cells and their capacity to metastasize in vivo in mouse models." (PMID 29156643, 2017). "The same group has shown that human melanoma ABCB5+ subpopulation preferentially expresses the vasculogenic differentiation markers like Tie1 and CD144 (VE-cadherin) which are distinct from those expressed on mature CD31+ tumor endothelial cells." (PMID 28137308, 2017). "It is important to note that the optimal detection of ABCB5 at the level of melanoma cells require the isolation of these cells through techniques that do not involve the use of trypsin." (PMID 29156643, 2017). "Subsequent studies support the involvement of CSCs in human melanoma progression using ABCB5 and CD271 as markers." (PMID 28137308, 2017). "Transcripts of MLANA, TYR, MAGEA3, PAX3, and ABCB5 were successfully identified from a single melanoma cell, as reflected by the increase in reciprocal Ct values (1/Ct)." (PMID 28978038, 2017). "The effect of ΔNp73 on ABCB5 expression was further confirmed in metastases from melanoma patients and in the melanoma-derived cell line SK-MEL-28." (PMID 28677036, 2017). "In fact, it was shown that in melanoma-initiating cells ABCB5 controls UK-IL1-β secretion, which acts to maintain slow-cycling, chemoresistant cells through a signaling pathway mediated by the IL-1/βIL-8/CXCR1 signaling axis." (PMID 29156643, 2017). "Another study showed that the membrane transporter conferring multi drug resistance (MDR-1) was expressed in a minority of melanoma cells displaying in vitro clonogenic properties; interestingly, these cells co-express ABCB5." (PMID 29156643, 2017). "ABCB5, a tumour initiating or “stem cell” marker known to be involved in tumour resistance to chemotherapy and targeted therapy in melanoma, identifies a subset of slow-cycling tumour cells with increased potential to initiate metastases." (PMID 28978038, 2017). "The evidence that a vast majority of melanoma CTCs express “stem cell” markers such as ABCB5, shown by flow cytometry and PAX3, by gene expression, argues for inclusion of such markers to increase the CTC detection rate by immunocytochemistry." (PMID 28978038, 2017). "By expression of the chemoresistance determining factor ABCB5 a novel type of CSCs has been identified that is known as malignant melanoma initiating cells (MMIC)." (PMID 28785557, 2017).
melanoma (continued). "Subsequent work has shown that ABCB5 identifies CICs in malignant melanoma that correlate with clinical disease progression and that can be specifically targeted to abrogate tumor growth." (PMID 34221246, 2017). "This revealed that cell populations expressing melanoma initiating markers, such as ABCB5 and RANK, are more common amongst CTCs than in the matching tumour, suggesting a preferential selection for certain tumour cell subtypes in the blood." (PMID 28978038, 2017). "For instance, ABCB5 has been identified as a molecular marker of melanoma CSCs, and administration of anti‐ABCB5 mAb can substantially inhibit tumor formation and neoplastic progression." (PMID 28191780, 2017). "Knockdown of tenascin-C elicited a dramatic decrease of the ABCB5-positive side population of melanoma cells, and markedly increased the sensitivity of melanoma cells to doxorubicin." (PMID 29156643, 2017). "Additional studies have shown that ABCB5+ melanoma cells overexpress the vasculogenic differentiation markers CD144 and Tie1 and are associated with vasculogenic mimicry." (PMID 29156643, 2017). "The expression of ABCB5 on melanoma cells was confirmed through the immunohistochemical analysis of primary tumor tissues." (PMID 29156643, 2017). "On the other hand, ABCB5 blockade induced cellular differentiation of melanoma cells, reversed their resistance to multiple chemotherapeutic drugs, and impaired their tumorigenesis in vivo." (PMID 29156643, 2017). "Recently, ABCB5+ cells in melanoma have shown to suppress T cell activation and thus have specific role for immune evasion." (PMID 28137308, 2017). "ABCB5 was also found to be the most commonly expressed marker by melanoma CTCs detected by flow cytometry in unenriched and enriched samples." (PMID 28978038, 2017). "Expression of the multidrug resistance mediator, ABCB5, in CICs has been characterized in previous studies on human melanoma and hepatocellular carcinoma." (PMID 34221246, 2017). "The results revealed that caffeic acid phenethyl ester (CAPE), a bioactive molecule induces apoptosis in ABCB5 knocked down CD133+ chemoresistant melanoma cells." (PMID 28137308, 2017). "For example, ABCG2 is overexpressed in breast CSCs, ovarian CSCs overexpress ABCB1 and malignant melanoma initiating cells (MMIC) express high levels of ABCB5." (PMID 29117122, 2017). "ABCB5 expression was also correlated with resistance to doxorubicin, camptothecin, and 5-FU in malignant melanoma and hepatocellular carcinoma." (PMID 34221246, 2017). "In melanoma tissues, ABCB5 and NF-κβ expression are positively correlated, and ABCB5 was shown to activate NF-κβ activity, promoting p65 protein stability." (PMID 29156643, 2017). "The melanoma-initiating marker ABCB5 remained the most common marker after slanted enrichment and was observed to be more highly represented after enrichment than the other CTC markers." (PMID 28978038, 2017). "ABCB5+ melanoma cells were shown to be capable of tumorigenesis, self-renewal, and differentiation into a heterogeneous cell population when primary patient-derived tumor cells were serially transplanted into NOD/SCID mice." (PMID 29156643, 2017). "Our NMR data, showing significantly reduced expression of pyruvate and lactate in ABCB5-KD G3361 melanoma cells, indicated a potential role of ABCB5 in regulating the glycolysis pathway as well as the Warburg effect, a metabolic hallmark of most cancer cells." (PMID 27560924, 2016). "Although ABCB5 has been extensively studied in diverse human malignancies, few investigated ABCB5 in murine melanoma." (PMID 26910836, 2016). "The possibility of glycolysis modulation by an ABCB5-dependent IL1β-mediated mechanism was supported by functional studies employing monoclonal antibody (mAb)-dependent ABCB5 protein inhibition in wildtype G3361 melanoma cells." (PMID 27560924, 2016). "Out of four, two ABC transporter protein expressions, ABCG2 and ABCB5, have been identified in potential melanoma stem cells." (PMID 27054115, 2016).
melanoma (continued). "Genes (e.g. BRN2, POU2F3, and SOX10) expressed in melanoblasts, and those (e.g. JARID1B, CD271, and ABCB5) which help to endow melanoma cells with stem-like properties and cellular plasticity, are also in this network." (PMID 27149382, 2016). "This implicates that ABCB5 serves as a key driver of murine melanoma aggressiveness, but more work need to be done to elucidate the mechanism." (PMID 26910836, 2016). "The expression of ABCB5 strongly overlapped with clinical tumor progression, therapeutic resistance, and recurrence in malignant melanoma." (PMID 26910836, 2016). "To further prove the potential of ABCB5 as a CSC marker in murine melanoma cells, we sorted B16F10 (CD44+CD133+CD24+) by FACSAriaTM III which have been proved to have biological characteristics of CSC." (PMID 26910836, 2016). "Paclitaxel and doxorubicin have been reported to be closely related to drug resistance and ABCB5 expression in melanoma." (PMID 26910836, 2016). "Glycolysis, glutaminolysis and phospholipid metabolism were significantly modulated by the expression of the ATP-binding cassette transporter, ABCB5, a cell-surface marker for melanoma initiating cells." (PMID 27560924, 2016). "This is concurrent with our present finding that expression of the MIC marker ABCB5 modified PL metabolism of G3361 melanoma cells in a similar characteristic manner under normoxic conditions." (PMID 27560924, 2016). "We have also demonstrated that pentoxifylline markedly reduced the frequency of ABCB5 (ATP-binding cassette, sub-family B, member 5)-positive cells that are considered as melanoma-initiating cells." (PMID 27351373, 2016). "To elucidate the functional role of ABCB5 in murine melanoma growth, we silenced ABCB5 in B16F10 by shRNA." (PMID 26910836, 2016). "ABCB5 has already been demonstrated in chemo resistant stem cells, as well as drug efflux transportation of doxorubicin in human melanoma." (PMID 27584160, 2016). "It was also observed upon APP downregulation in melanoma cells that there was lower expression of ABCB5 (doxorubicin-resistant transporter), which has been implicated in chemoresistance." (PMID 26840089, 2016). "The tumor volumes of mice inoculated with B16F10 (shABCB5) significantly decreased compared with the respective controls, demonstrating that ABCB5 performs a functional role in murine melanoma growth." (PMID 26910836, 2016). "For example, the CSC surface markers CD44+ and CD24− were defined in breast cancer, CD20+ and ABCB5+ in melanoma, and EpCAM+, CD44+, and CD166+ in colon cancer." (PMID 27172898, 2016). "Together with our recent demonstration of ABCB5-mediated regulation of IL-1β secretion in human melanoma cells, these results suggest that the glycolysis pathway in melanoma cells is potentially regulated by an ABCB5/IL-1β/HIF-1α/PFKP signaling cascade." (PMID 27560924, 2016). "We found that besides glycolytic metabolites, also the PDE levels were significantly increased by expression of the MIC marker ABCB5 for G3361 melanoma cells under normoxic culture conditions." (PMID 27560924, 2016). "This comprehensive study presents, for the first time, the relevance of the expression of a cell surface marker of melanoma-initiating cells, ABCB5, for the cellular metabolome." (PMID 27560924, 2016). "Significant differences between levels of phosphorylated water-soluble metabolites in ABCB5-WT and ABCB5-KD G3361 melanoma cells based on 31P NMR spectroscopy of cell extracts." (PMID 27560924, 2016). "ABCB5-WT G3361 melanoma cells were characterized by a higher total amount of water-soluble metabolites per total protein than ABCB5-KD G3361 cells." (PMID 27560924, 2016). "Considering that ABCB5 is a promising target for melanoma therapy, we selected VNP20009 carrying shRNA against ABCB5 to inhibit the melanoma growth in mice." (PMID 26910836, 2016).